LINC00426 (long independently transcribed non-coding RNA 426)
Gene: Long non-coding RNA gene on chromosome 13 (30,316,360 to 30,377,145, reverse strand). Ensembl gene ENSG00000238121.
Diseases named in the same sentence as LINC00426 in open-access papers:
LINC00426 is named in the same sentence as 18 diseases in open-access papers, as found by Europe PMC text mining. Sharing a sentence is not in itself a finding about the gene and the disease. The quoted sentences say what the papers report.
breast carcinoma (3 papers, 2020 to 2025). "For example, LINC00426 was found to be upregulated in TNBC, non-TNBC, and HER2-positive breast cancer patients and downregulated in patients with colorectal carcinoma, non-small-cell lung carcinoma, and lung squamous cell carcinoma." (PMID 33204302, 2020).
hepatocellular carcinoma (2 papers, 2023 to 2025). A malignant tumor that arises from hepatocytes. "LINC00426 is known to be associated with lung adenocarcinoma (LUAD) progression, doxorubicin resistance in osteosarcoma (OSA), immune-cell infiltration in clear cell renal cell carcinoma (ccRCC) and prognosis in hepatocellular carcinoma (HCC) patients." (PMID 37260772, 2023).
lung adenocarcinoma (2 papers, 2021 to 2022). A carcinoma that arises from the lung and is characterized by the presence of malignant glandular epithelial cells. "For instance, LINC00426 was significantly upregulated in lung adenocarcinoma and played a notable role in accelerating tumor proliferation, invasion, metastasis, and EMT in vitro and in vivo." (PMID 35004851, 2021). "For example, linc00426 may act as a ceRNA, which effectively suppresses the expression of miR-455-5p, thereby modulating the derepression of UBE2V1, a target gene of miR-455-5p in lung adenocarcinoma." (PMID 35578597, 2022).
lung squamous cell carcinoma (2 papers, 2020). "LINC00426 expression level in lung squamous cell carcinoma was lower than that of tumor tissue; however, the LINC00426 relative expression level was statistically different between the different clinical stages of lung cancer patients (P < 0.05)." (PMID 31691516, 2020). "However, LINC00426 expression was not correlated with the DFS and OS for lung squamous cell carcinoma." (PMID 31691516, 2020).
non-small cell lung carcinoma (2 papers, 2020 to 2023). A group of at least three distinct histological types of lung cancer, including non-small cell squamous cell carcinoma, adenocarcinoma, and large cell carcinoma. "Moreover, high expression of LINC00426 is associated with improved overall survival (OS) in non-small cell lung cancer (NSCLC) and LUAD." (PMID 37260772, 2023).
osteosarcoma (2 papers, 2020 to 2025). A usually aggressive malignant bone-forming mesenchymal neoplasm, predominantly affecting adolescents and young adults. "LINC00426 has been concerned in an occasional circumstance when we made the investigation of osteogenesis (a main research interests of our group), we ought to explore the functions and underlying mechanisms of LINC00426 in osteosarcoma." (PMID 32620145, 2020). "Previous research reported elevated LINC00426 was associated with osteosarcoma tumorigenesis and pulmonary metastasis, which indicated LINC00426 may play an oncogenic role in osteosarcoma, so we chose LINC00426 for further study." (PMID 32620145, 2020). "Here we set out to characterize the expression status of LINC00426 in osteosarcoma and understand its mechanistic involvement in incidence of doxorubicin (Dox) resistance." (PMID 32620145, 2020).
acute myeloid leukemia (1 paper, 2020). Acute myeloid leukemia (AML) is a group of neoplasms arising from precursor cells committed to the myeloid cell-line differentiation. "LINC00426 relative expression level was not statistically different between the tumor tissue and corresponding normal tissue in most of the malignant carcinomas, except for diffuse large B‐cell lymphoma (DLBCL), acute myeloid leukemia (AML), and thymoma (THYM)." (PMID 31691516, 2020).
liver cancer (1 paper, 2024). An epithelial or non-epithelial malignant neoplasm that arises from the liver. "LINC00426 is known to be related to immune infiltration level in liver cancer." (PMID 38978021, 2024).
lung carcinoma (1 paper, 2020). "We found that LINC00426 was downregulated in tumor tissue compared to normal lung tissue of the non‐small cell lung cancer patients and correlated with poor prognosis." (PMID 31691516, 2020). "For lung cancer, the LINC00426 relative expression was not statistically different between cancer tissue and normal tissue (P > 0.05)." (PMID 31691516, 2020).
lymph node metastasis (1 paper, 2020). "The results showed that the expression of Linc00426 was more prominent in LUAD tissues with lymph node metastasis compared with those without." (PMID 33311443, 2020).
tumor (8 papers, 2020 to 2023). "In the present study, we identified Linc00426 highly expressed in LUAD by microarray, suggesting Linc00426 may function as an extensive tumor promoter." (PMID 33311443, 2020). "These 8 lncRNAs (AL365361.1, LINC01934, AC090152.1, PCED1B-AS1, LINC00426, AC007728.2, AC243829.4, and LINC00158) were found to be positively correlated with immune cells of the tumor microenvironment." (PMID 35719925, 2022). "Previous studies have shown that LINC00426 and SNHG16 can promote tumor development and participate in the regulation of TIME." (PMID 35571063, 2022). "Interestingly, the qRT-PCR results indicated that the expression of AC012065.1, LINC01116, TMCC1-AS1 and LINC01060, was significantly higher in tumor tissue while expression of AC002511.2, LINC00426 and ARHGAP31-AS1 was similar between tumor and normal tissue." (PMID 36387100, 2022).
cancer (3 papers, 2020 to 2023). A tumor composed of atypical neoplastic, often pleomorphic cells that invade other tissues. "Previous reports demonstrated that LINC00426 promotes LUAD progression and doxorubicin resistance in OSA, suggesting a potential oncogenic role of LINC00426 in these cancers." (PMID 37260772, 2023). "Future studies might consider evaluating the prognostic role of LINC00426 between diverse cancer subtypes to determine potential differences, as we identified between PAM50 BRCA subtypes." (PMID 37260772, 2023). "We propose that LINC00426 expression could have a cancer type-dependent prognostic role." (PMID 37260772, 2023).
LINC00426 also shares sentences with these, for which no sentence is quoted: colorectal carcinoma (1 paper); diffuse large B-cell lymphoma (1); genetic disorder (1); multiple myeloma (1); pancreatic carcinoma (1); thymoma (1).